REN (renin)
Diseases named in the same sentence as REN in open-access papers (continued):
Sharing a sentence is not in itself a finding about the gene and the disease.
electrolyte imbalance (3 papers, 2023 to 2025). "The renin-angiotensin-aldosterone system (RAAS) is also dysregulated, resulting in an increase in angiotensin II, which leads to vasoconstriction, high blood pressure, increased vascular permeability, and electrolyte imbalance." (PMID 38690475, 2024).
gastrointestinal disorders (3 papers, 2020 to 2025). "The final prediction model, ADAPTiP, included nine predictors: age, chronic lung disease, the primary presenting complaints of respiratory, bleeding and gastrointestinal disorders and syncope on hospital admission and antithrombotics, diuretics, and renin–angiotensin–aldosterone system drug classes." (PMID 39821882, 2025).
peripheral neuropathy (3 papers, 2022 to 2025). A disorder affecting the peripheral nervous system. "While the etiology of orthostatic intolerance has not yet fully been uncovered, it has been associated with multiple underlying pathological processes, including peripheral neuropathy, altered renin–aldosterone levels, hypovolemia, and autoimmune processes." (PMID 38673062, 2024). "POTS is theorized to be the culmination of multiple underlying pathological processes, including peripheral neuropathy/denervation, hypovolemia with altered renin–aldosterone levels, and a hyperadrenergic state." (PMID 38673062, 2024).
bacterial infection (2 papers, 2021 to 2023). "KEGG analysis showed that NETs-related DEGs was mainly associated with IL-17 signaling pathway, various hormones (including renin, epinephrine, oxytocin, estrogen) signaling pathway, myocardial contraction and bacterial infection." (PMID 37304069, 2023).
neurological diseases (2 papers, 2011 to 2025). "Among them, neural receptor–ligand interactions, calcium channels, and the renin–angiotensin system are closely related to neurological diseases." (PMID 40001962, 2025).
brain disorder (1 paper, 2025). A disease affecting the brain or part of the brain. "Of the significant reverse MR relationships, the brain disorders demonstrated associations with the increased expression of six proteins (PAMR1, MAVS, F11R, REN, GER and LEPR) and decreased expression of three proteins (TNFRSF4, BTN2A1, ENPP6)." (PMID 40456753, 2025).
hematological disorders (1 paper, 2025). "After 12 months of follow-up, the patient was treated with maximal tolerated doses of renin-angiotensin system inhibitors combined with Nefecon, the patient’s urine protein decreased significantly and renal function was stable, and no hematological disorders were found during the follow-up." (PMID 41195171, 2025).
REN also shares sentences with these, for which no sentence is quoted: acute myocardial infarction (14 papers); hypertrophy (11); Hypocalciuria (11); Glomerular sclerosis (8); immune dysfunction (8); alcoholism (6); bladder cancer (6); cardiac arrhythmias (6); metabolic acidosis (6); glomerulopathy (5); hepatorenal syndrome (5); nephritis (5); nephrocalcinosis (5); peripheral arterial disease (5); polycystic kidney disease (5); prion disease (5); Sleep apnea (5); toxoplasmosis (5); autosomal dominant polycystic kidney disease (4); Chagas disease (4); erythrocytosis (4); Failure to thrive (4); pertussis (4); proliferative diabetic retinopathy (4); Salmonella Infections (4); thyroid cancer (4); viral myocarditis (4); angina (3); autoimmune thyroid disease (3); benign tumor (3).
A further 237 diseases each share a sentence with REN in 3 papers or fewer.